PIK3CA (phosphatidylinositol-4,5-bisphosphate 3-kinase catalytic subunit alpha)
Diseases named in the same sentence as PIK3CA in open-access papers (continued):
Sharing a sentence is not in itself a finding about the gene and the disease.
breast cancer (continued). "In animal models, HS‐10352 markedly suppressed the growth of transplanted tumors in a dose‐dependent manner in mice bearing gastric cancer HGC‐27 (PIK3CA E542K) and human breast cancer HCC‐1954 (PIK3CA H1047R) tumors." (PMID 38037839, 2023). "In the aspect of copper regulation, PIK3CA was reported to be relative to glioma, breast cancer, and medulloblastoma." (PMID 36973786, 2023). "Treatment with buparlisib (PI3Kα/β/δ/γ inhibitor) reduced the expression of Wnt target genes AXIN2, LEF1, and MYCN in human PIK3CA-mutant ER+ breast cancer cells." (PMID 37471270, 2023). "Alpelisib is an α-specific class I PI3K inhibitor that inhibits the phosphorylation of downstream PI3K target proteins, including AKT, and it also inhibits the growth of PIK3CA mutant breast cancer cell lines in vitro and in vivo." (PMID 37469415, 2023). "Mutations in the p110α catalytic subunit of phosphatidylinositol 3-kinase (PI3K), encoded by the PIK3CA gene, cause dysregulation of the PI3K pathway in 35–40% of patients with HR+/HER2– breast cancer." (PMID 37101291, 2023). "PIK3CA mutations occur in around 10% of early TNBC, and their frequency increases in metastatic forms, reflecting a subset of originally ER+ breast cancer that relapse, losing their ER expression, and thus becoming “secondary” TNBC." (PMID 36934165, 2023). "Recent evidence has highlighted the significance of PIK3CA mutation as the primary mutation associated with BCBrM, and the essential role of SREBP1 in promoting breast cancer cell proliferation in the brain." (PMID 37491281, 2023). "All three combinations proved promising in PIK3CA aberrant basal-like breast cancer in the mouse models." (PMID 36900375, 2023). "The univariate cox analysis (p < 0.01) and prognostic value analyses showed that the PGK1and PIK3CA, whose expression ware significantly up-regulated in breast cancer, has a certain prognostic value for breast cancer patients." (PMID 37524857, 2023). "INPP4B overexpression increased activated-β-catenin and Wnt target gene expression in PIK3CA-mutant ER+ human breast cancer cells." (PMID 37471270, 2023). "The results demonstrated that patients with HER2+/PIK3CA mutated breast cancer achieved a significantly lower pCR rate than patients with HER2+/PIK3CA wild-type breast cancer." (PMID 37469415, 2023). "Across solid tumours, PIK3CA mutations (PIK3CAmut) are commonly observed in hormone receptor‐positive, HER2‐negative (HR+, HER2−) breast cancers, with a prevalence of ~ 40%." (PMID 36892268, 2023). "In the phase III CLEOPATRA trial the progression-free survival after first-line dual HER2 blockade with trastuzumab plus pertuzumab was shorter in patients with PIK3CA mutant breast cancer than in patients with wild-type (WT) PIK3CA tumors." (PMID 37469415, 2023). "We selected PIK3CA, which, like KRAS, is also one of the commonly mutated proto-oncogenes in human cancers—in human breast cancer, it is mutated in 36% of all cases, the highest among mutated proto-oncogenes." (PMID 37172086, 2023). "Capivasertib, a pan‐AKT inhibitor, reached an ORR of just 4% in PIK3CA‐mutant breast cancer patients." (PMID 38037839, 2023).
breast cancer (continued). "It would be important to investigate how PIK3CA mutations and PTEN loss, key genetic alterations in this drug resistance-associated pathway, relate to response to preoperative therapy in early breast cancer." (PMID 37106324, 2023). "Mammary tumors arose in 30% of mouse mammary tumor virus (MMTV)-PIK3CA-H1047R mice and 13% of MMTV-PIK3CA-E545K mice." (PMID 37247123, 2023). "Overall, our study revealed that alpelisib is effective against PIK3CA-mutant CMT, similar to its effectiveness against PIK3CA-mutated human breast cancer." (PMID 38033642, 2023). "The combination of BYL-719 plus everolimus, an mTOR inhibitor, has been studied in PIK3CA mutant breast cancer cell lines previously and was reconfirmed through this study." (PMID 36900375, 2023). "In PIK3CA-mutant ER+ breast cancer cells, INPP4B localizes prominently to late endosomes via its interaction with the small GTPase Rab7." (PMID 37471270, 2023). "We further analyzed all available plasma-cfDNA and CTC-derived gDNA samples from the three breast cancer patients (Pt#11, Pt#12, Pt#13) that developed metastasis at different time points for ESR1 and PIK3CA mutations." (PMID 36690653, 2023). "Recent advances in next‐generation sequencing (NGS) have shed light on genomic alterations underlying breast cancer subtypes and paved the way for successful development of targeted therapies such as PIQRAY® (alpelisib) for certain PIK3CA mutations." (PMID 36495126, 2023). "A breast cancer cell line (MCF7) and a NSCLC cell line (H1975) with a mutated PIK3CA gene were also included in the experiments." (PMID 38033496, 2023). "Although pivotal in breast cancer biology and evolution, ESR1 and PIK3CA mutations clinically are simplistically dichotomized as mutated or wild type." (PMID 37784176, 2023). "This combination is only approved for patients with ER+ HER2- breast cancer that are male or post-menopausal female with PIK3CA mutant after disease progression after or while being treated with endocrine-based treatment." (PMID 36900375, 2023). "The MEN1611-mediated p110α depletion occurs selectively in PIK3CA mutant breast cancer cell lines at a concentration range in which cytotoxic effects are observed." (PMID 36913051, 2023). "Comparison of clinical and molecular characteristics between PIK3CA wild-type and mutant breast cancer." (PMID 37747019, 2023). "Studies have identified a number of feedback mechanisms that limit alpelisib efficacy, including PI3K reactivation by p110β in HER2-amplified and PIK3CA-mutant breast cancers." (PMID 37471270, 2023). "PIK3CA gene mutation is abandoned in HR + and HER + breast cancer; while it is less frequent in TNBC." (PMID 37415164, 2023). "Basket trials have been conducted to evaluate the effectiveness of adding alpelisib, a specific p110α PIK3CA inhibitor to the hormonal treatment for PIK3CA mutant luminal breast cancer patients." (PMID 37397557, 2023). "In PIK3CA-mutant ER+ breast cancer, PI3Kα signaling promotes INPP4B-dependent lysosomal degradation of GSK3β, which enhances Wnt/β-catenin activation." (PMID 37471270, 2023). "Here, we characterized a subgroup of luminal breast cancer expressing co-mutations in ARID1A and PIK3CA genes and identified their effect on important signaling pathways." (PMID 38017109, 2023).
breast cancer (continued). "Characteristics of the ER+/HER2-breast carcinoma samples included in the first PIK3CA testing round." (PMID 36825198, 2023). "In the present study, the expression of the PIK3CA gene was upregulated in control adjacent tissue in comparison with breast carcinoma tissue." (PMID 37821962, 2023). "In breast cancer, the combined mutation frequency of PTPRT and PIK3CA in metastatic breast cancer was significantly higher than in primary cancer (q = 0.025)." (PMID 35789644, 2022). "Alpelisib in clinical trials demonstrated a favorable safety profile and antitumor activity in patients with PIK3CA-altered advanced solid cancers, including PIK3CA-mutant breast cancer." (PMID 35408658, 2022). "Activating mutations in PIK3CA, the gene that encodes the catalytic subunit of the PI3K enzyme (most notably residues 545 and 1047), are frequently found in luminal and HER2 + breast cancer cells." (PMID 35365185, 2022). "PIK3CA mutations are detected in approximately 40% of estrogen receptor (HR+) and epidermal growth factor receptor 2 (HER2-) breast cancers." (PMID 36109789, 2022). "PIK3CA G1049R mutation (COSV55874453) is considered to be a structural damaging alteration as disease-causing drivers in breast cancer." (PMID 35379811, 2022). "This indicates that PIK3CA can be used as a prognostic molecular biomarker and therapeutic target for breast cancer." (PMID 36568197, 2022). "This proof-of-principle study evaluated the concordance rate for PIK3CA assessment between breast cancer primary tumors and matched metastases and the consensus among NGS and RT-PCR for this type of molecular testing." (PMID 36428975, 2022). "High Akt activity was found to be a predictive biomarker of sensitivity to ipatasertib (GDC-0068) in PTEN/PIK3CA-mutant MCF breast cancer cells." (PMID 36046843, 2022). "PIK3CA H1047R, in contrast, only produced sporadic tumors after 12 months, which is opposite to findings in breast cancer." (PMID 34748271, 2022). "As the first PI3K inhibitors were emerging in the clinic, we and others studied their effects on ER signaling with the goal of identifying the most effective combinatorial therapy for ER+/PIK3CA mutant breast cancer." (PMID 35774123, 2022). "The safety and efficacy of alpelisib in combination with fulvestrant were evaluated in the phase 3 SOLAR-1 trial of patients with PIK3CA-mutated, hormone receptor-positive (HR+), HER2– advanced breast cancer who had received prior endocrine therapy." (PMID 35016012, 2022). "Currently, only a liquid biopsy blood test, for detecting the PIK3CA mutation, is approved by the FDA for breast cancer that can be used in clinical practice." (PMID 35565189, 2022). "Negative ctDNA results are typically reflexed to tissue genotyping for NSCLC and testing for PIK3CA in hormone receptor-positive (HR+) breast cancers." (PMID 35486650, 2022). "The PIK3CA gene, which codes for the catalytic subunit of the PI3K signalling protein, is the most frequently mutated oncogene in breast cancer, with mutations present in 35–40% of samples." (PMID 35055414, 2022). "PIK3CA (encoding p110α, the catalytic subunit of PI3K) oncogenic mutations are involved in various types of cancer, such as colorectal cancer, breast cancer, ovarian cancer, hepatocellular carcinoma, and hidradenoma papilliferum." (PMID 36172495, 2022). "Detection of PIK3CA mutations from ctDNA in locally recurrent unresectable or metastatic HR–positive and HER2-negative breast cancer can be treated with phosphatidylinositol 3-kinase inhibitor, alpelisib plus fulvestrant." (PMID 35884530, 2022).
breast cancer (continued). "In BCCuS-low group, the mutation frequency of PIK3CA, CDH1, MAP3K1 up-regulated, these genes have been reported as tumor suppressor in breast cancer." (PMID 36699089, 2022). "For example, PIK3CA mutant breast cancer tumor cells displayed dramatically elevated AA and eicosanoid levels, promoting tumor cell proliferation." (PMID 35705959, 2022). "We reported that INPP4B expression is increased in up to 46% of ER+ breast cancer relative to normal breast tissue, correlating with mutant PIK3CA expression." (PMID 36612130, 2022). "The benefit of alpelisib in PIK3CA-mutated, hormone-receptor-positive, HER2-negative advanced breast cancer highlights the increasing clinical importance of PIK3CA testing." (PMID 36011273, 2022). "Downregulation of RNMT selectively inhibits the proliferation of PIK3CA mutant breast cancer cell lines, suggesting that cap methylation is required for PIK3CA mutated cancer cells." (PMID 35886072, 2022). "The BEECH trial investigated the efficacy of combining capivasertib, an AKT inhibitor, with the first-line chemotherapeutic paclitaxel in metastatic breast cancers that were HER2-positive and HER2-negative and harbored PIK3CA mutations." (PMID 35887191, 2022). "Taselisib is a selective PI3Kα inhibitor and yields antitumor activity toward PIK3CA‐mutant tumors, especially for breast cancer." (PMID 36254250, 2022). "A phase 1 basket study evaluated the clinical actionability of taselisib in PIK3CA-mutant breast cancers, but results showed low clinical actionability of single-agent taselisib therapy." (PMID 35216405, 2022). "The PIK3CA regulates the formation of PI3K, one of the most commonly mutated genes in breast cancer." (PMID 36276152, 2022). "As of 2019, alpelisib is FDA approved for the treatment of metastatic PIK3CA-mutant, HR+ breast cancers in combination with the estrogen receptor (ER) antagonist fulvestrant." (PMID 36970726, 2022). "Mutated PIK3CA and AKT and loss of PTEN are commonly found in breast cancer, leading to uncontrollable cell growth, proliferation, survival and non-responsiveness to TAM therapy." (PMID 36293165, 2022). "From an unselected cohort of 1270 breast cancer patients (PiA, Prognostic Assessment in routine application, NCT 01592825) 1123 tumours were tested for the three PIK3CA hotspot-mutations H1047R, E545K, and E542K by qPCR." (PMID 36279023, 2022). "In particular, homologs AKT1, AKT2, ERBB2, FGFR2, and PIK3CA in CGC play important roles in breast cancer progression, mediating breast cancer risk, corresponding to the driver candidates RPS6KA1, SGK1, PTK2, IGF1R, PIK3CB, and PRKDC predicted by DriverMP." (PMID 38091511, 2022). "Twenty-eight out of 42 evaluable patients had PIK3CA mutations, among whom the confirmed ORR was 14.3% (4/28) with a confirmed response observed in patients with breast cancer (2/5, 40%) and ovarian cancer (2/5, 40%), and a DCR of 46.4% (13/28)." (PMID 36385120, 2022). "Phosphatidylinositol 3-kinase catalytic subunit A (PIK3CA) gene mutation is observed in approximately 40% of HR-positive and HER2-negative breast cancers." (PMID 36209184, 2022). "Compared with wild-type (WT) PIK3CA, paxalisib produces a significant response in the treated PIK3CA-mutant (MT) breast cancer cell line." (PMID 35614940, 2022). "The publication of results from the pivotal phase III SOLAR-1 trial eventually led to the approval of alpelisib in combination with fulvestrant for patients with PIK3CA-mutant, ER+ advanced breast cancer, and prior exposure to ET." (PMID 36046843, 2022). "The mutation in PIK3CA, which encodes the p110α catalytic subunit of the PI3K, is the most prevalent in HR+ breast cancer." (PMID 35482141, 2022).
breast cancer (continued). "PIK3CA/AKT1/PTEN alterations are frequently observed in breast cancer, including approximately 50% of patients with hormone receptor-positive (HR+) breast cancers, and contribute towards a negative prognosis and resistance to endocrine therapies." (PMID 34860318, 2022). "More recently, in patients with metastatic ER+/PIK3CA mutant breast cancer, the addition of the PI3Kα inhibitor alpelisib was approved in combination with fulvestrant." (PMID 35774123, 2022). "The SOLAR-1 trial found that adding alpelisib, a PI3Kα-specific inhibitor, provided a progression-free survival benefit and OS improvement in PIK3CA-mutated, hormone receptor-positive, HER2-negative advanced breast cancer patients." (PMID 35444614, 2022). "For example, the co-existence of PIK3CA mutation, PTEN deletion and HER2 amplification is detected in breast cancer." (PMID 36010585, 2022). "Of relevance in ER+/HER2- advanced breast cancer, the therascreen PIK3CA RGQ PCR kit detects PIK3CA mutations to help direct PI3Ka inhibitor treatment (alpelisib)." (PMID 36176758, 2022). "H1047R (PIK3CA), E545K (PIK3CA), E17K (AKT1), and N345K (PIK3CA) produced recurrent neoantigens and had a higher mutation frequency in the breast cancer cohort." (PMID 35387130, 2022). "Meanwhile, PIK3CA mutation and PTEN loss trigger estrogen‐independent growth of breast cancer cells." (PMID 38089455, 2022). "Mutations in PIK3CA, part of the gene for PI3K, have been identified in up to 36% of hepatocellular carcinoma, 26% of breast cancer and 26% of colon cancer." (PMID 36286049, 2022). "PIK3CA-activating or PTEN-inactivating mutations, which are two of the most frequent genetic alterations in breast cancer, lead to abnormal PI3K pathway activation and subsequently increase phosphatidylinositol 3,4,5-triphosphate (PIP3) levels." (PMID 36139701, 2022). "Together, our results provide preclinical data in support of Bcl-xL inhibition as a potential clinical strategy for radiosensitization of PIK3CA/PTEN wild-type breast cancers with low expression of Mcl-1." (PMID 36381235, 2022). "In advanced breast cancer (BC), approximately 40% of hormone-receptor-positive, HER2-negative BC cases harbor druggable PIK3CA mutations suitable for combined alpelisib/fulvestrant treatment." (PMID 35682999, 2022). "For example, alpelisib, a drug targeting PIK3CA mutant breast cancer in phase II clinical trials 68 displays antitumor activity in pre-initiation studies." (PMID 36313041, 2022). "It is also reported by clinical studies on mutation analysis in patients with breast cancer in China that PIK3CA is also common in Chinese patients with breast cancer, with a prevalence of 32%–46.5%." (PMID 38089455, 2022). "One of the patients in the 40 mg CYH33 treatment group, a 45-year-old female with breast cancer (Luminal B, HER2-, PIK3CA E545K mutation), had a rapid and remarkable response to CYH33." (PMID 36385120, 2022). "The development and use of drugs targeting PIK3CA to block the PI3Ks pathway will play an effective role in the treatment of breast cancer." (PMID 36568197, 2022). "The high sensitivity of breast cancer cells to ipatasertib is often related to the loss of PTEN and PIK3CA mutation, which has a bright prospect in the clinical treatment of TNBC." (PMID 35311116, 2022). "Of note, the population eligible for PIK3CA inhibition comprises a large portion of breast cancer patients with HER2-low disease." (PMID 36038884, 2022). "We aim to elucidate the prognostic value of PIK3CA mutations and copy number (CN) gain (PIK3CA-mut/gain) in hormone receptor-positive and HER2-negative (HR + /HER2−) breast cancer (BC)." (PMID 35181669, 2022).